RET (ret proto-oncogene)
Diseases named in the same sentence as RET in open-access papers (continued):
Sharing a sentence is not in itself a finding about the gene and the disease.
papillary thyroid carcinoma (248 papers, 1992 to 2026). "Pathogenic RET alterations, including mutations and fusions, drive oncogenesis, most notably medullary and papillary thyroid carcinomas and non-small cell lung cancer, by constitutively activating downstream RAS-MAPK, PI3K-AKT, and JAK-STAT signaling." (PMID 41977363, 2026). "Mutations in the RET/PTC oncogene have been reported to play an important role in the development of papillary carcinomas after radiation exposure." (PMID 40565992, 2025). "The most frequent driver mutation in both radiation-induced and sporadic papillary thyroid carcinoma comes from the genome rearrangements between the RET gene and the PTC genes (CCDC6 and NCOA4), located close to each other on chromosome 10." (PMID 40362680, 2025). "Unlike the more common RET mutations found in medullary thyroid carcinoma (MTC) and MEN2, the most prevalent pro-carcinogenic variant of the RET gene in papillary thyroid carcinoma (PTC) is RET rearrangement." (PMID 40269951, 2025). "No genetic mutations relating to the occurrence of the solid variant of papillary thyroid carcinoma, including RET/PTC rearrangements and mutations in the BRAF or RAS, were detected by a gene panel test, namely, the OncomineTM Dx Target test." (PMID 38023212, 2023). "RET/PTC rearrangements were seen in about 10%–20% of papillary thyroid carcinomas, RET/PTC1 was associated with a more indolent behavior, and RET/PTC3 mutations were related to more aggressive behavior." (PMID 35197932, 2022). "RET fusions were found in 10–20% of papillary thyroid cancers and 1–2% of NSCLC, while RET point mutations occur in approximately 60–90% of advanced medullary thyroid cancers (MTC)." (PMID 33109256, 2020). "Clinical-pathological characteristics according to the status of BRAF, RAS, and TERT mutations and RET rearrangements in papillary thyroid carcinomas." (PMID 32425887, 2020). "The most prevalent examples of fusion genes caused by radiation-induced genotoxic stress are RET fusions found in irradiation-induced papillary thyroid carcinoma." (PMID 31007851, 2019). "In this exploratory analysis, positive RET staining by IHC was associated with a low risk of recurrence and death from papillary thyroid cancer." (PMID 30552739, 2019). "Oncogenic RET point mutations and RET fusions occur mainly in papillary thyroid cancer and lung adenocarcinoma." (PMID 27050078, 2016). "RET rearrangement was first shown to be associated with papillary thyroid carcinoma (PTC), leading to the fusion oncoprotein (RET/PTC) and constitutive activation of RET receptor tyrosine kinase in papillary cancer cells." (PMID 25881079, 2015). "The mutually exclusive B-RAF V600E mutation and RET/PTC rearrangements are most prevalent in papillary thyroid carcinomas (∼70% of all PTCs), and appear to be involved in the neoplastic transformation of follicular thyroid cells." (PMID 24797369, 2014). "At present, the best known mutation form in papillary thyroid cancer is RET/PTC1 and RET/PTC3 sequence, also encountered in Hashimoto’s thyroiditis." (PMID 24407910, 2014). "Gene rearrangements over RET oncogene activation and mutations were common in post-Chernobyl papillary carcinomas in children." (PMID 24512315, 2014). "The aim of this case-control study was to determine the effect of four well known RET single nucleotide polymorphisms (SNPs) on the risk for differentiated thyroid carcinoma." (PMID 25330015, 2014). "The aim of this study was to determine the contribution of the G691S, L769L, S836S and S904S RET polymorphisms to the genetic susceptibility to differentiated thyroid carcinoma in the Portuguese population." (PMID 25330015, 2014). "Further, rearrangements of the RET gene papillary thyroid carcinoma (RET/PTC) are associated with PTC commonly seen in tumors of children and tumors associated with radiation exposure." (PMID 23455356, 2013).
papillary thyroid carcinoma (continued). "Aberrant RET signaling has been associated with papillary thyroid carcinoma, multiple endocrine neoplasia types 2 syndromes, and Hirschsprung's disease." (PMID 24036517, 2013). "In papillary thyroid carcinoma, genetic alterations such as RET/TRK rearrangements or BRAF and RAS mutations usually lead to signaling derangements in the mitogen-activated protein kinase pathway." (PMID 23165002, 2013). "More than 20 years ago, RET gene was shown to be associated with papillary thyroid carcinoma (PTC) through chromosomal rearrangements (RET/PTC)." (PMID 22928112, 2012). "Certain RET gene SNPs were shown to be associated with an increased risk of differentiated thyroid cancer." (PMID 23185308, 2012). "Recently, BAY-43-9006 has shown potent inhibition of RET, RET V804L, and RET V804M, which are associated with medullary and papillary thyroid carcinomas." (PMID 20161827, 2008). "The RET kinase represents a suitable target for novel drugs helpful in the treatment of both medullary and papillary thyroid cancers, in which activating mutations in the RET proto-oncogene have been identified." (PMID 19578508, 2008). "Human rearranged RET/PTC3 (papillary thyroid carcinoma) proto-oncogene and high-risk human papillomavirus (HPV) type 16 E7 oncogene induces in the mouse a neoplastic transformation of thyroid follicular cells." (PMID 18985036, 2008). "Somatic rearrangements of RET designated as RET/PTC (from papillary thyroid carcinoma) were identified in papillary thyroid carcinoma before RET was recognized as the susceptibility gene for MEN2." (PMID 17997826, 2007). "In particular, RET/PTC3 is associated with such post-Chernobyl papillary thyroid carcinomas of solid variant and short latency." (PMID 16641909, 2006). "RET fusions and mutations, common in medullary and some papillary thyroid cancers, can be effectively treated with selective RET inhibitors such as selpercatinib and pralsetinib, which have demonstrated high response rates and favorable tolerability compared to older multikinase inhibitors." (PMID 41228293, 2025). "A study of papillary thyroid cancer (PTC) biopsies in 2001 identified different splice variants in the RET extracellular domain described as in-frame changes with preservation of the tyrosine kinase domain (RET 1/8, RET 2/8, RET 3/8)." (PMID 38566816, 2024). "An inversion on chromosome 10 resulting from improper recombination of RET and H4 genes is associated with papillary thyroid cancer; although these genes are separated by a great linear distance, their proximity in the nucleus allows for this rearrangement to occur." (PMID 38276232, 2024). "B-Raf proto-oncogene - Ras proto-oncogene point mutations and rearranged during transfection (RET) gene fusions, which are the most frequently activated oncogenes in papillary thyroid cancer (PTC), activate the mitogen-activated protein kinase (MAPK) signalling pathway." (PMID 36326389, 2022). "Moreover, diverse papillary thyroid cancer cell lines harboring RET/PTC rearrangements or BRAF V600E mutation had higher osteopontin expression in comparison to normal thyroid cells." (PMID 34680488, 2021). "Papillary carcinoma of the thyroid is characterized by a high prevalence of RET chromosomal rearrangements, and of point mutations of RAS or BRAF proto-oncogenes, all of which are able to trigger the activation of mitogen-activated protein kinase (MAPK) cascade, as well as NTRK fusions." (PMID 33277509, 2020). "It is unclear whether common genetic variants of the RET proto-oncogene contribute to disease susceptibility, clinical severity, and thyroid function in differentiated thyroid cancer (DTC)." (PMID 29131865, 2017). "Interestingly, in primary papillary thyroid carcinomas, positive for the RET/PTC1 rearrangement, the loss of CCDC6 keeps high levels of pCREB1-S133." (PMID 23145146, 2012).
papillary thyroid carcinoma (continued). "The molecular pathogenesis of papillary thyroid carcinomas (PTC) is largely associated with genetic alterations in the RET-RAS-RAF-MAPK pathway usually caused by RET/PTC rearrangements (13%–43%) or activating point mutations in the BRAF (29%–83%) or RAS-family genes (0 %–21 %)." (PMID 22682753, 2012). "Likewise, the association of nuclear shape irregularities and specific molecular alterations that contributed to increased malignancy have been established in some other cancers, such as papillary thyroid carcinoma with RET fusion and EGFR mutated lung adenocarcinomas." (PMID 38972973, 2024). "One of the most common radiation induced human papillary thyroid cancers (PTC) is characterized by the fusion of the intracellular kinase-encoding domain of RET to the first 101 amino acids of a gene named Coiled Coil Domain Containing 6 (CCDC6) which gives rise to the oncogene named RET/PTC1." (PMID 22655027, 2012). "Research examining pediatric cohorts revealed associations between RET/PTC1 and classical papillary thyroid carcinoma morphology, while solid variant PTC tumors demonstrated greater prevalence of RET/PTC3 rearrangements." (PMID 40469184, 2025). "In the second study of nine healthcare workers with papillary thyroid carcinoma (PTC) exposed to LDIR, BRAF V600 genetic alterations were revealed in four cases, including one with RET/PTC1 fusion, and in one case, point mutations and fusions were found." (PMID 39860597, 2025). "Another common genetic alteration in papillary thyroid cancer is the rearrangement of the RET gene, leading to the formation of RET/PTC fusion genes." (PMID 40344620, 2025). "RET fusions occur in ∼10% of papillary thyroid carcinomas (PTC), 1%–2% of non-small cell lung cancers (NSCLC), and rarely in other malignancies." (PMID 41181595, 2025). "Somatic RET fusion events have also been described in several cancers, including papillary thyroid cancer, non-small-cell lung cancer, breast cancer, salivary gland cancer and pancreatic cancer." (PMID 39655713, 2025). "It achieved ORR of 52.2% and 42.9% for RET-mutated MTC and RET-fusion-positive papillary thyroid cancer (PTC), respectively." (PMID 41278287, 2025). "Initially described by Fusco and colleagues, chromosomal rearrangement of RET was first documented in papillary thyroid carcinoma." (PMID 40469184, 2025). "Somatic RET fusions are characteristic of papillary thyroid carcinoma and lung adenocarcinoma and are less common in other tumor types." (PMID 41465145, 2025). "In contrast, conventional papillary carcinomas (those forming papillae) are predominantly associated with BRAF p.V600E or BRAF V600E-like mutations, including RET and NTRK rearrangements." (PMID 41175860, 2025). "RET-rearranged papillary carcinomas often display crowded papillae with few follicular structures, and some have the features of the diffuse sclerosing subtype of papillary carcinoma." (PMID 41175860, 2025). "Our findings suggest that complete inactivation of Dicer1 induces DNA damage accumulation and cell death in RET/PTC3-driven papillary thyroid carcinomas." (PMID 41002430, 2025). "In differentiated thyroid cancer, RET gene fusions account for approximately 6–10% of papillary thyroid cancer (PTC) cases and 6% of poorly differentiated thyroid cancer (PDTC) cases but are rare in anaplastic thyroid cancer (ATC) cases." (PMID 41278287, 2025). "RET fusions are recurrent somatic alterations in 6–20% of differentiated thyroid cancer (DTC) of papillary histology and occur in a smaller percentage (1–2%) of lung adenocarcinoma." (PMID 41465145, 2025). "Activating rearrangements of RET (rearranged during transfection) have been identified as oncogenic factors in several malignancies, including papillary thyroid carcinoma and NSCLC." (PMID 39166093, 2024).
papillary thyroid carcinoma (continued). "Fusions involving the gene RET followed by NTRK and ALK, are the most prevalent rearrangements found in pediatric papillary thyroid carcinoma (PTC) and have the highest association with invasive disease, particularly in cases of RET fusion." (PMID 39473507, 2024). "Although literature exploring histiocyte expression of RET is scarce, one study evaluated RET expression by immunohistochemistry in 50 cases of papillary thyroid cancer and found that in 26/50 (52%), adjacent histiocytes stained positive for RET." (PMID 38804700, 2024). "The RET/PTC rearrangement is a genetic change that contributes to the development of papillary thyroid carcinoma, the most frequent kind of thyroid cancer." (PMID 38501105, 2024). "To illustrate, a study identified a HOOK3:RET fusion in an instance of papillary thyroid cancer, demonstrating its oncogenic potential through a mouse xenograft cancer model." (PMID 38228617, 2024). "Mann-Whitney U tests and Kruskal-Wallis test of the predictive marker with relative RET mRNA expression levels in papillary thyroid carcinoma." (PMID 37188126, 2023). "RET fusions have been described in patients with papillary thyroid carcinoma, accounting for approximately 20–40% of sporadic cases, with a higher frequency of RET fusions observed after radioiodine exposure." (PMID 38201460, 2023). "The two tumor types with the highest number of RET fusion were lung adenocarcinoma and thyroid papillary carcinoma, and they had a prevalence rate 1.14% (455/39,922) and 9.09% (109/1199), respectively." (PMID 36690680, 2023). "The most common molecular alterations in papillary thyroid carcinomas are BRAF (62%)—predominantly, BRAFV600E—RAS (13%), RET-PTC (7%), and TERT promoter mutation (9%)." (PMID 36980552, 2023). "The two tumor types with the highest number of RET fusion were lung adenocarcinoma and thyroid papillary carcinoma and they had prevalence rates of 1.14% (455/39922) and 9.09% (109/1199), respectively." (PMID 36690680, 2023). "These rearrangements are associated with papillary thyroid carcinoma cases with different characteristics; CCDC6::RET is more associated with sporadic thyroid cancer and with older patients and classic subtypes of papillary carcinoma." (PMID 37188126, 2023). "RET fusions are seen in fewer than 10% of papillary thyroid cancers and approximately 2% of NSCLC tumours, similar to the incidence of ROS1 fusions." (PMID 37277734, 2023). "The RET/PTC3 transgenic mice model, in which the expression of the RET/PTC3 oncogene is targeted to the thyroid and which develops a solid variant of papillary thyroid carcinoma, represents a suitable model of human PTC." (PMID 37445942, 2023). "Somatic RET pathogenic variants and RET rearrangements have been also reported in sporadic MTC, papillary thyroid carcinoma, and multiple neoplasms." (PMID 37626640, 2023). "RET/PTC have been observed in papillary carcinomas and shown to activate the RAS-MAPK pathway in a ligand-independent way." (PMID 37375228, 2023). "RET rearrangements first described in papillary thyroid carcinoma are generally known as “RET/PTC”, of which the most frequently detected are RET/PTC1 and RET/PTC3." (PMID 37761374, 2023). "On the other hand, RET rearrangements are described in papillary thyroid carcinoma, non-small cell lung carcinoma, and other sporadic types of cancers." (PMID 36358717, 2022). "GOLGA5 is a RET proto-oncogene interacting gene; its gene fusion pattern is characteristic of patients with papillary thyroid carcinomas who were exposed at young age to radioiodine released from the Chernobyl reactor." (PMID 36088851, 2022). "The index patient’s tumor had an intermediate thyroid differentiation score and clustered with other RET-rearranged papillary thyroid cancers." (PMID 35510953, 2022). "Among RET fusion-positive cancers, lung adenocarcinomas predominated (81%), followed by papillary thyroid cancers (12%), and finally a variety of five other unique cancer types." (PMID 35304457, 2022).
papillary thyroid carcinoma (continued). "The Cancer Genome Atlas (TCGA) papillary thyroid cancer cohort contains a well-annotated set of 402 primary papillary thyroid cancers, including 25 RET-rearranged cases." (PMID 35510953, 2022). "RET alterations were first identified in the late 1980s with the detection of an oncogenic RET fusion in papillary thyroid carcinomas." (PMID 35957881, 2022). "First, gene fusions that contain the RET kinase domain produce constitutively active chimeric RET homodimers that drive cancer growth, and these fusions are most commonly present in non-small cell lung cancers and in papillary thyroid cancers." (PMID 35304457, 2022). "In differentiated thyroid cancer, the most common genetic changes include BRAF and RAS mutations and RET rearrangement." (PMID 34986823, 2022). "Other potential targetable genetic alterations were found in less than 10% cases: the RET gene fusion was found in 8%, NTRK1 and 3 gene fusion in 3%, and other mutations in less than 2% of classic papillary thyroid cancers." (PMID 34630336, 2021). "In a previous study, silencing RET gene expression using siRNA suppressed EMT in papillary thyroid carcinoma cells has also been reported." (PMID 34209165, 2021). "Chromosomal rearrangement resulting in fusing RET protein appears to play an oncogenic role in 20% of papillary thyroid carcinomas." (PMID 33485291, 2021). "Instead, RET fusions, occurring at the somatic level, are typical of papillary thyroid carcinoma, lung adenocarcinoma, and few other cancers." (PMID 32326537, 2020). "Papillary carcinoma, in particular, is mostly related to mutations that activate the MAPK signalling pathway, including RET/PTC rearrangements and point mutations of the BRAF and RAS genes." (PMID 32722293, 2020). "Gene fusion was the first mechanism identified for the oncogenic activation of the receptor tyrosine kinase RET (REarranged during Transfection), initially discovered in papillary thyroid carcinoma (PTC)." (PMID 32326537, 2020). "RET was first discovered in papillary thyroid carcinoma, and later in sporadic tumors, neurodegenerative diseases, and Hirschsprung’s disease." (PMID 32235589, 2020). "The most common RET fusions, in papillary thyroid carcinoma (PTC) and in lung adenocarcinoma (LADC) are CCDC6-RET and NCOA4-RET (primarily in PTC) and KIF5B-RET (primarily in LADC)." (PMID 32326537, 2020). "Mutation-selective kinase inhibitor such as RET-inhibitor selpercatinib is FDA-approved for the treatment of metastatic RET-mutant MTC or RET-fusion mutant differentiated thyroid cancers with phase II clinical trial showing an overall response rate of 70%." (PMID 33158279, 2020). "CCDC6–RET and NCOA4–RET are the most commonly identified RET fusions in papillary thyroid cancers where RET rearrangements seem to be correlated with a more aggressive phenotype." (PMID 31731495, 2019). "Similar spatial proximity during interphase has been proposed to mediate RET and H4 fusion in papillary thyroid carcinoma, and TMPRSS2 and ERG in prostate cancer." (PMID 31007851, 2019). "RET fusions mostly occur in irradiation-induced papillary thyroid carcinoma as well as in lung adenocarcinoma." (PMID 31007851, 2019). "RET fusion genes are thought to be oncogenic drivers and they are detected in 20–40% of all papillary thyroid cancers." (PMID 29088743, 2017). "CCDC6 was first identified as a gene frequently rearranged with the RET tyrosine kinase gene in papillary thyroid cancers." (PMID 28653990, 2017). "RET/PTC rearrangement, BRAF, NRAS, and KRAS mutations are considered to be mutually exclusive in papillary thyroid carcinoma." (PMID 28493027, 2017). "In our cohort, the most frequent second malignancy in RET exon 8 carriers was papillary thyroid carcinoma (PTC), accounting for 69% of the cases of second malignancy." (PMID 28951487, 2017).